NR2F1 (nuclear receptor subfamily 2 group F member 1)
Diseases named in the same sentence as NR2F1 in open-access papers (continued):
Sharing a sentence is not in itself a finding about the gene and the disease.
prostate carcinoma (17 papers, 2012 to 2026). A carcinoma that arises from epithelial cells of the prostate gland. "The orphan nuclear receptor NR2F1, commonly mutated in cancers, was shown to be epigenetically upregulated downstream of TGFb/p38 signalling in murine models of dormancy, as well as in DTCs isolated from long-term prostate cancer patients." (PMID 37608096, 2023). "Finally, the orphan nuclear receptor NR2F1 has been linked to tumor cell dormancy in prostate cancer through induction of pluripotency genes, such as SOX2 and NANOG." (PMID 32220301, 2020). "A new pilot study (NCT03572387) is assessing the use of retinoic acid (RA) 5-AZA and ATRA in prostate cancer patients to prolong dormancy by inducing a quiescent expression signature through activation of NR2F1." (PMID 37608096, 2023). "CRISPR deletion of NR2F1 was able to restore enzalutamide sensitivity in androgen receptor (AR)-positive prostate cancer LNCaP cell with chromodomain helicase DNA-binding protein 1 (CHD1) knockdown." (PMID 36230565, 2022). "Furthermore, androgen deprivation treatment in prostate cancer has been linked to upregulation of NR2F1, suggesting that certain commonly used therapies may induce dormancy and cooperate in a long-term response by affecting the DTCs and the host to enter a pro-dormancy state." (PMID 30322396, 2018). "Notably, NR2F1 agonists have been investigated in other cancer types (e.g., breast and prostate cancer models) to induce tumor cell dormancy, but their effectiveness and translational potential in melanoma models are currently unexplored." (PMID 40955667, 2025). "In addition, a number of established quiescence mechanisms are conserved across cancer types; for example, increased p38:ERK signalling ratio, NR2F1 and p27 have all been shown to be dormancy-inductive in head and neck squamous cell carcinoma, breast and prostate cancers." (PMID 34439077, 2021). "A combination of 5-azacytidine and all-trans retinoic acid (ATRA) increased expression of nuclear receptor subfamily 2 Group F member 1 (NR2F1) maintaining dormancy via SOX9 and retinoic acid receptor (RAR)β in prostate cancer and HNSCC." (PMID 41091336, 2025). "Orphan nuclear receptor NR2F1 was shown to be a critical node for dormancy induction in head and neck squamous cell carcinoma (HNSCC) and in DTCs of prostate cancer patients." (PMID 33987095, 2021). "Clinically, it is unknown whether NR2F1 plays a role in resistance in other BRAF-mutant cancers (e.g., colorectal, thyroid) or dormancy in solid tumors like breast or prostate cancer." (PMID 40955667, 2025).
Intellectual disability (13 papers, 2017 to 2025). "In 2014, NR2F1 (nuclear receptor subfamily 2, group F, member 1) mutations were first associated with optic atrophy and intellectual disability by Bosch and Schaaf." (PMID 40217317, 2024). "The lncRNA lnc-NR2F1 is a conserved lncRNA that was recently found to be associated with autism spectrum disorder and intellectual disability in children and it has been observed that the lnc-NR2F1 locus is frequently mutated in these patients." (PMID 34203457, 2021). "As recently shown, mutations/deletions in the NR2F1 locus lead to a rare hereditary form of ON atrophy associated with intellectual disability, epilepsy, and autism, named Bosch‐Boonstra‐Schaaf optic atrophy (BBSOA) syndrome." (PMID 31318166, 2019). "Bosch-Boonstra-Schaaf optic atrophy syndrome (BBSOAS) is a rare, autosomal dominant neurodevelopmental disorder caused by pathogenic variants in NR2F1, characterized by developmental delay, intellectual disability, optic nerve anomalies and autism spectrum disorder." (PMID 40855817, 2025). "NR2F1 was first linked to OA with intellectual disability in 2014." (PMID 40217317, 2024). "The disruption of NR2F1 may influence the neurodevelopment of the visual system and cause optic atrophy with intellectual disability." (PMID 34573359, 2021). "Disruption of NR2F1 underlies core features of BBSOAS, including intellectual disability, visual impairment, epilepsy, and autistic traits." (PMID 41283372, 2025). "A long non-coding RNA called lnc-NR2F1 regulates several neuronal genes, including some involved in autism and intellectual disabilities." (PMID 30777838, 2019). "In humans, mutations in the NR2F1 gene cause Bosch-Boonstra-Schaaf optic atrophy syndrome (BBSOAS), a rare neurodevelopmental disorder characterized by multiple clinical features including vision impairment, intellectual disability and autistic traits." (PMID 37260288, 2023).
Bosch-Boonstra-Schaaf optic atrophy syndrome (12 papers, 2017 to 2026). Optic atrophy-intellectual disability syndrome is a rare, hereditary, syndromic intellectual disability characterized by developmental delay, intellectual disability, and significant visual impairment due to optic nerve atrophy, optic nerve hypoplasia or cerebral visual impairment. "Bosch-Boonstra-Schaaf optic atrophy syndrome, triggered by mutations in the nuclear receptor subfamily 2 group f member 1 (NR2F1) gene, is a rare neurodevelopmental disorder." (PMID 40537021, 2026). "As mentioned in the study, mutations in the NR2F1 gene lead to a rare neurodevelopmental disorder, Bosch-Boonstra-Schaaf optic atrophy syndrome." (PMID 40537021, 2026). "Aberrant NR2F1 causes the rare neurodevelopmental disorder Bosch-Boonstra-Schaaf Optic Atrophy Syndrome." (PMID 40204944, 2025). "A recently described monogenic neurodevelopmental syndrome named Bosch-Boonstra-Schaaf Optic Atrophy Syndrome (BBSOAS) is caused by NR2F1 haploinsufficiency." (PMID 34975398, 2021). "To investigate cochlear-specific regulatory interactions at the Nr2f1 locus implicated in Bosch-Boonstra-Schaaf optic atrophy syndrome (BBSOAS) and the accompanying hearing loss phenotype, we visualized chromatin contact maps at 10 kb resolution on chromosome 13." (PMID 41169613, 2025). "NR2F1 mutations are associated with Bosch-Boonstra-Schaaf optic atrophy syndrome (BBSOAS)." (PMID 40217317, 2024). "Mutations in the NR2F1 gene lead to an emerging NDD, called Bosch-Boonstra-Schaaf optic atrophy syndrome (BBSOAS), a condition characterized by cognitive and visual impairments." (PMID 39485283, 2024). "NR2F1 mutations are responsible for the Bosch-Boonstra-Schaaf optic atrophy syndrome (OMIM #615722; BBSOAS), whereas SOX2 mutations cause micro- or anophtalmia (OMIM #206900, Microphtalmia, syndromic 3; optic nerve hypoplasia and abnormalities of the central nervous system)." (PMID 40631402, 2025). "Variations in the NR2F1 gene in Bosch-Boonstra-Schaaf optic atrophy syndrome not only affect mitochondrial dynamics but also directly target genes important for mitochondrial DNA transcription and translation." (PMID 40537021, 2026).
head and neck squamous cell carcinoma (12 papers, 2018 to 2024). A squamous cell carcinoma that arises from any of the following anatomic sites: lip and oral cavity, nasal cavity, paranasal sinuses, pharynx, larynx, and salivary glands. "The orphan nuclear receptor (NR2F1) regulates tumor cell dormancy in head and neck squamous cell carcinoma (HNSCC) by coordinating the hypermethylation of H3 histone proteins (H3K27, H3K9, and H3K4), bounded to SOX9, RARβ, and CDK inhibitors to inhibit cell proliferation." (PMID 38994941, 2024). "More relevant, the treatment with this agonist resulted in inhibition of lung metastasis in head and neck squamous cell carcinoma (HNSCC) mouse models, supporting the use of NR2F1 agonists to induce dormancy as a therapeutic strategy to prevent metastasis." (PMID 37369946, 2023). "In PCa and head and neck squamous cell carcinoma (HNSCC) models, NR2F1 induced a dormant phenotype by regulating the H3K4me3 and H3K27me3 epigenetic marks in the promoter of SOX9 and RARβ." (PMID 34208521, 2021). "In this respect, epigenetic upregulation of orphan nuclear receptor NR2F1 is detected in DTCs from the breast, and prostate cancer patients harboring lifelong dormant disease and in experimental latency models of head and neck squamous cell carcinoma (HNSCC)." (PMID 31430951, 2019). "The hypoxic microenvironment in primary head and neck squamous cell carcinomas (HNSCC) and breast tumors induces the selection of a fraction of cells that concomitantly express hypoxia-related genes (GLUT1 and HIF-1α) and long-term dormancy genes, such as NR2F1, DEC2, and p27." (PMID 35158815, 2022). "They report that hypoxia enhances the expression of key dormancy genes like NR2F1, DEC2, p27 in head and neck squamous cell carcinoma (HNSCC) and primary breast tumor." (PMID 29616190, 2018).
developmental delay (10 papers, 2013 to 2025). "In this study, we report MRI brain scans of six novel patients carrying de novo NR2F1 variants localized along the whole gene sequence and characterized by developmental delay, behavioral disorders, speech difficulties, and autistic‐like traits." (PMID 32484994, 2020). "The most common neuroanatomical malformation found in patients with ONH is hypoplasia of the corpus callosum associated with developmental delay, neurological deficits and seizures, which are all clinical features observed in children carrying disease-causing NR2F1 variants." (PMID 34466801, 2021). "Developmental disorders caused by mutations in GATAD2B (OMIM 615074), ADNP (OMIM 615873), BCOR (OMIM 300166) and NR2F1 (OMIM 615722) have features that overlap with those of TBR1-related disorder, including developmental delay, ID, speech and language impairments and autistic behaviors." (PMID 36579832, 2023).
optic atrophy (10 papers, 2019 to 2025). A disorder characterized by loss of optic nerve fibers. "A subsequent functional study confirmed the pathogenic nature of NR2F1 variants and their association with syndromic optic atrophy." (PMID 34466801, 2021). "BBSOAS is a neurodevelopmental disorder caused by mutations in the NR2F1 gene, associated with several symptoms, including optic atrophy, hypotonia, seizure and ID, that might be compatible with mitochondrial dysfunction in the nervous system." (PMID 37260288, 2023). "NR2F1 was another gene that could be associated with optic atrophy." (PMID 34573359, 2021). "A previous report focused on the optic atrophy defect, an important component of the clinical phenotype, but nothing was known on whether NR2F1 haploinsufficiency would lead to particular types of cortical malformations." (PMID 32484994, 2020). "In light of our findings, the mitochondrial abnormalities recently observed in the optic nerve and retina of constitutive Nr2f1-knockout/Nr2fl-HET mice might be a direct consequence of NR2F1 altered function that could contribute to the optic atrophy observed in BBSOAS mouse models." (PMID 37260288, 2023).
breast tumors (8 papers, 2014 to 2022). "In order to investigate this, we studied the spatial distribution of NR2F1-positive tumor cells relative to macrophages in fixed primary breast tumors." (PMID 35110548, 2022). "The cancer stem cell-related pathways, as well as metastasis-related pathways, were enriched in the NR2F1-high expressing bulk breast tumor." (PMID 35740627, 2022). "Among the top-ranked differentially expressed genes between these two RNA-seq datasets, CELF2 and NR2F1 were consistently decreased in HR-deleted breast tumors, but upregulated in HR-expressing MDA-MB-231 cells." (PMID 36230572, 2022). "Conversely, residual dormant tumor cells after treatment were reported to be associated with tumor heterogeneity, whereas intratumor heterogeneity was less in the high NR2F1-expressing breast tumors in TCGA." (PMID 35740627, 2022). "The NR2F1 high-expression bulk breast tumors in the cohorts we analyzed were consistent with suppressed cell proliferation, higher expression of dormancy-related genes, and enrichment of pathways as observed in the previous reports." (PMID 35740627, 2022). "Expression of NR2F1 was lower in breast tumors with high Ki67 expression and proliferation scores." (PMID 36230565, 2022). "In order to prove that CAF-expressed NR2F1 regulates breast tumor dormancy, one needs to analyze the single-cell sequencing data and show whether the late recurrence in other organs, such as lungs, bones, and brain, other than lymph nodes, is correlated with NR2F1 expression in CAFs." (PMID 35740627, 2022). "This approach revealed that the combined abundance of VAV family (VAV2+VAV3) transcripts does show an inverse correlation with the expression levels of both NR2F1 and ZEB2 (red bars) mRNAs in luminal breast tumors." (PMID 30087437, 2019). "However, the findings from our study are not ample enough to substantiate that CAF-expressed NR2F1 regulates breast tumor dormancy." (PMID 35740627, 2022).
autism spectrum disorder (6 papers, 2019 to 2025). A spectrum of developmental disorders that includes autism, and Asperger syndrome. "Recent work reports interactions between rare genetic variants, placental sex differences, and steroid-related traits in autism spectrum disorder, highlighting a promising avenue for future research on steroid-associated mechanisms in NR2F1-related neurodevelopment." (PMID 41283372, 2025).
epilepsy (5 papers, 2022 to 2025). A brain disorder characterized by episodes of abnormally increased neuronal discharge resulting in transient episodes of sensory or motor neurological dysfunction, or psychic dysfunction. "BBSOAS, a rare neurodevelopmental disorder caused by pathogenic variants in NR2F1, is characterized by DD/ID, visual impairment, hypotonia, epilepsy, behavioral anomalies such as autistic traits, and other manifestations." (PMID 39972940, 2025). "Although NR2F1-related epilepsy was first reported in 2015, most studies on NR2F1 mutation-related BBSOAS have focused on visual impairment, ID/DD and psychobehavioral disorders." (PMID 40217317, 2024). "Epilepsy caused by NR2F1 mutations was first reported in 2015, which expanded the clinical manifestations of BBSOAS." (PMID 40217317, 2024). "As an example, a patient with an NR2F1 mutation in the DBD was initially identified in an epilepsy study on infantile spasms." (PMID 35455940, 2022). "Experimental models carrying patient-specific NR2F1 mutations may be needed to fully explore the underlying mechanisms of NR2F1-related epilepsy." (PMID 40217317, 2024). "The NR2F1 pathogenic variants in our six cases are also provided, including two novel mutations, which expand the clinical phenotypes and genotypes of NR2F1-related epilepsy in BBSOAS." (PMID 40217317, 2024). "The NR2F1 gene is starting to emerge from unbiased exome-sequencing approaches in individuals with epilepsy, and is associated with West syndrome, a severe form of infancy epilepsy characterized by clusters of spasms." (PMID 35455940, 2022). "We propose the inclusion of NR2F1 in the diagnostic NGS gene panels for epilepsy, which could help families in their diagnostic odyssey to efficient clinical assignment." (PMID 35455940, 2022). "Thus, mutations of NR2F1 may affect neurogenesis and the functions of GABAergic neurons, leading to an excessive increase in cortical excitability, and finally epilepsy." (PMID 40217317, 2024). "We only recruited BBSOAS patients with NR2F1-related epilepsy; therefore, the number of patients recruited was relatively small." (PMID 40217317, 2024). "Based on this experience, the following patient 6 was treated with perampanel as an initial ASM when he was diagnosed with NR2F1-related epilepsy (DD, visual impairment, infantile spasm and WES presenting NR2F1 de novo variant)." (PMID 40217317, 2024). "Our results showed that the NR2F1-related epilepsies were mostly IESS (65%), which generally occurs within six months of life and is difficult to control." (PMID 40217317, 2024). "Although NR2F1-related epilepsy was previously resistant to multiple anti-seizure medications and steroids, in our patients, perampanel exhibited dramatic effects on NR2F1-related epilepsy." (PMID 40217317, 2024). "In this study, we summarized the characteristics of 20 cases of NR2F1-related epilepsy with detailed epilepsy records (including our six new cases and 14 previously reported cases) to analyze the epileptic symptoms and treatment outcomes." (PMID 40217317, 2024). "In this paper, we comprehensively summarized the clinical characteristics, treatments and outcomes of NR2F1-related epilepsy for the first time." (PMID 40217317, 2024). "By combining the six cases and 14 previously reported cases, we analyzed the characteristics and treatment outcomes of NR2F1-related epilepsy." (PMID 40217317, 2024). "In summary, in this paper we summarize the clinical characteristics of NR2F1-related epilepsy, including treatments and outcomes." (PMID 40217317, 2024). "Although ~ 46.7% of BBSOAS patients present with epilepsy, which is always drug-resistant and associated with higher rates of behavioral and cognitive problems, the treatment and outcomes of NR2F1-related epilepsy have rarely been described." (PMID 40217317, 2024). "Previously, ASMs for NR2F1-related epilepsy were selected according to the epilepsy syndrome and seizure type owing to the lack of specific and effective drugs." (PMID 40217317, 2024).
epilepsy (continued). "Consistently, a patient with frameshift variant and truncation in the NR2F1 LBD has been reported to show a severe phenotype, including epilepsy." (PMID 35455940, 2022). "In all of our six cases, perampanel effectively controlled the NR2F1-related epilepsy." (PMID 40217317, 2024). "Perampanel exhibits dramatic efficacy for NR2F1-related epilepsy." (PMID 40217317, 2024). "Therefore, for patients with triad presentation including epilepsy, ID/DD, and vision defects, NR2F1 sequencing should be conducted in a timely manner for early precision treatment." (PMID 40217317, 2024). "Second, we did not conduct any experiments to verify our hypothesis that the effectiveness of perampanel on NR2F1-related epilepsy is due to the enhancement of pyramidal neurons and weakening of interneurons." (PMID 40217317, 2024). "Infantile epileptic spasms was the most common seizure type of NR2F1-related epilepsy." (PMID 40217317, 2024). "The effectiveness of perampanel and TPM in our cases further supports the hypothesis that NR2F1-related epilepsy is due to the increased excitability and number of pyramidal neurons, as well as decreased number and aberrant migration of interneurons." (PMID 40217317, 2024). "This indicates that perampanel combined with TPM may be an effective combinational regimen for NR2F1-related epilepsy." (PMID 40217317, 2024). "To gain a better understanding of NR2F1-related epilepsy, we included only BBSOAS patients with seizures in our epilepsy clinic." (PMID 40217317, 2024). "Thus, considering the high seizure control rate in our patients (100%) compared with traditional treatments for corresponding epilepsy syndrome (e.g., ACTH and vigabatrin for IESS), we suggest that perampanel could be considered as the first-choice ASM for NR2F1-related epilepsy." (PMID 40217317, 2024). "In fact, long before NR2F1 haploinsufficient patients were grouped in this syndrome, BBSOAS patients were included in autism, epilepsy or other clinical cohorts, depending on their most prominent pathological features." (PMID 35455940, 2022).
lung carcinoma (4 papers, 2018 to 2025). "Moreover, nuclear receptor subfamily 2 group F member 1 (NR2F1) expression has been specifically linked to lung cancer dormancy." (PMID 41303477, 2025). "In lung cancer models, Sosa MS and colleagues demonstrated that Nuclear Receptor Subfamily 2 Group F Member 1 (NR2F1) is commonly downregulated via promoter hypermethylation during active tumor proliferation, whereas it is significantly upregulated during cellular dormancy." (PMID 41303477, 2025).